PAFAH1B3 (platelet activating factor acetylhydrolase 1b catalytic subunit 3)
Diseases named in the same sentence as PAFAH1B3 in open-access papers (continued):
Sharing a sentence is not in itself a finding about the gene and the disease.
osteosarcoma (continued). "Therefore, the results suggested that silencing of PAFAH1B3 suppresses tumorigenicity of osteosarcoma." (PMID 34136395, 2021). "Overall, these findings suggest that PAFAH1B3 is overly expressed in osteosarcoma." (PMID 34136395, 2021). "Moreover, the basal expression level of PAFAH1B3 is relatively high in the selected osteosarcoma cell lines (U-2 OS and MNNG/HOS)." (PMID 34136395, 2021). "To summarize, PAFAH1B3 could be suggested as a promising therapeutic target for osteosarcoma patients." (PMID 34136395, 2021). "This study demonstrated the biological function of PAFAH1B3 on osteosarcoma proliferation." (PMID 34136395, 2021). "This research suggested that PAFAH1B3 could be a novel therapeutic target for osteosarcoma patients." (PMID 34136395, 2021). "PAFAH1B3 was overexpressed in osteosarcoma tissues and cell lines." (PMID 34136395, 2021). "Furthermore, the proliferative effect of PAFAH1B3 in osteosarcoma was related to the regulation of the expression of EIF4EBP1, MYC, PTGS2 and RPS6KB1." (PMID 34136395, 2021). "Above all, the features of cancer-related PAFAH1B3 could be used for diagnosis and prognostic prediction of osteosarcoma." (PMID 34136395, 2021). "However, the roles and the regulating mechanisms of PAFAH1B3 in osteosarcoma progression remain unclear." (PMID 34136395, 2021). "Therefore, the invasive and metastatic effect of PAFAH1B3 in osteosarcoma remains further studies." (PMID 34136395, 2021). "In order to perform in vitro experiments, we selected two osteosarcoma cell lines (U-2 OS and MNNG/HOS) and analyzed corresponding PAFAH1B3 expression by using qRT-PCR." (PMID 34136395, 2021). "However, the biological role of PAFAH1B3 in osteosarcoma has not been elucidated yet." (PMID 34136395, 2021).
Ataxia (2 papers, 2017 to 2023). Ataxia refers to impaired coordination of voluntary muscle movement. "AHR is involved in the regulation of biological responses to planar aromatic hydrocarbons; UBE2L6 targets abnormal or short-lived proteins for degradation; and PAFAH1B3 functions in brain development and is associated with mental retardation, ataxia, and atrophy of the brain." (PMID 28178176, 2017).
hepatocellular carcinoma (2 papers, 2021 to 2023). A malignant tumor that arises from hepatocytes. "The link between T-cell exhaustion (TEX) and PAFAH1B3 in hepatocellular carcinoma (HCC) remains unknown, even though both of them are related to overall survival." (PMID 38063949, 2023).
mesothelioma (2 papers, 2021). A usually malignant and aggressive neoplasm of the mesothelium which is often associated with exposure to asbestos. "OS, DSS, and PFI analysis of various cancer types showed that increased PAFAH1B3 expression correlated with poor overall survival for ACC, LIHC, LUAD, mesothelioma (MESO), sarcoma (SARC), and SKCM, and poor DSS in BLCA, SARC, LIHC, LUAD, MESO, and SKCM." (PMID 35187070, 2021).
papillary thyroid carcinoma (2 papers, 2024 to 2025). "PAFAH1B3 is linked to the metastasis of thyroid papillary cancer via the EMT pathway." (PMID 41009369, 2025). "Moreover, PAFAH1B3 was linked to the metastasis of thyroid papillary cancer via the EMT pathway." (PMID 39553628, 2024).
Alzheimer disease (1 paper, 2025). A progressive, neurodegenerative disease characterized by loss of function and death of nerve cells in several areas of the brain leading to loss of cognitive function such as memory and language. "Through this analysis, we identify three understudied proteins—Tagln2, Slc25a3, and Pafah1b3—that may contribute to the differential sensitivity of Wistar Han rats and C57BL/6 mice to STZ-icv and may play a role in the development and progression of Alzheimer’s disease." (PMID 40450637, 2025).
colorectal tumour (1 paper, 2018). "PAFAH1B3 has been proposed as a driver cancer gene, while AHCYL2, which is highly expressed in the gastrointestinal tract, has been found to be highly downregulated in the gene expression profiling of colorectal tumour." (PMID 29304754, 2018).
coronary artery disease (1 paper, 2014). "Other genes in this region include CIC, which is a transcriptional suppressor involved in early organ development, CNFN (involved in hematopoiesis), CXCL17 (involved in angiogenesis), and PAFAH1B3 (related to coronary artery disease and organ development)." (PMID 24555826, 2014).
COVID-19 (1 paper, 2023). A disease caused by infection with severe acute respiratory syndrome coronavirus 2. "We showed a significant increase in the gene expression of PAFAH1B1 in the COVID-19 GCs group, but there was no change in the expression of PAFAH1B2 and PAFAH1B3." (PMID 36851787, 2023).
glioma (1 paper, 2020). A benign or malignant brain and spinal cord tumor that arises from glial cells (astrocytes, oligodendrocytes, ependymal cells). "Collectively, our experiments indicate that the MAFP-resistant TAMRA-FP signal in the tumor is principally due to neutrophil serine proteases migrating in the ~ 25 kDa band, while the bulk of MAFP-sensitive activity in glioma is likely due to PAFAH1b3 and PAFAH1b2." (PMID 32190011, 2020). "Future work should elucidate the role of PAFAH1b3 and PAFAH1b2 in glioma." (PMID 32190011, 2020).
hypopharyngeal squamous cell carcinoma (1 paper, 2021). "For example, in hypopharyngeal squamous cell carcinoma (HSCC), the expression of PAFAH1B3 was reported to be upregulated and was correlated with poor patient prognosis." (PMID 33732641, 2021).
leukemia (1 paper, 2022). A malignant (clonal) hematologic disorder, involving hematopoietic stem cells and characterized by the presence of primitive or atypical myeloid or lymphoid cells in the bone marrow and the blood. "Moreover, PAFAH1B3 loss in vivo sensitized leukemia cells to tyrosine kinase inhibitor (TKI) treatment via the platelet activating factor (PAF)/platelet activating factor receptor (PAFR) signaling pathway, and PAF/PAFR has been found to exhibit beneficial effects in some cancers." (PMID 35534807, 2022).
Lissencephaly (1 paper, 2023). A spectrum of malformations of cortical development caused by insufficient neuronal migration that subsumes the terms agyria, pachygyria and subcortical band heterotopia. "The molecular mechanism was associated with PAFAH1B3, which resulted to be inactive and hence, without capacity of interacting with LIS1 (related to lissencephaly), a member of the heterotrimeric G protein complex PAF-AH1B." (PMID 38003592, 2023).
melanoma (1 paper, 2021). A malignant, usually aggressive tumor composed of atypical, neoplastic melanocytes. "Blockers of PAFAH1B3 could heightened levels of tumor-suppressing lipids, then impairs pathogenicity of different cancers, including breast, ovarian, melanoma, and prostate cancer." (PMID 33767290, 2021).
multiple myeloma (1 paper, 2021). "High expression of PAFAH1B3 and SIAE, and low expression of PCED1B were identified as poor prognostic markers in patients with multiple myeloma, suggesting a role for these esterases in myeloma biology." (PMID 33531688, 2021).
myeloma (1 paper, 2021). "High expression of OVCA2, PAFAH1B3, USP4 and SIAE, and low expression of PCED1B, are poor prognostic markers in MM, suggesting a role for these esterases in myeloma biology." (PMID 33531688, 2021).
neuroblastoma (1 paper, 2021). Neuroblastoma (NB) is the most common solid, extracranial childhood tumor. "Similarly, selective small-molecule PAFAH1b3 inhibitors impaired the growth of neuroblastoma cells, suggesting that PAFAH1b3 might become a targetable oncoprotein." (PMID 33732641, 2021).
osteoarthritis (1 paper, 2021). A noninflammatory degenerative joint disease occurring chiefly in older persons, characterized by degeneration of the articular cartilage, hypertrophy of bone at the margins and changes in the synovial membrane. "Last but not least, although we have identified the correlation between PAFAH1B3 and osteoarthritis pathway, the detailed underlying mechanism remains unclarified in this study." (PMID 34136395, 2021).
pancreatic cancer (1 paper, 2024). "To verify this hypothesis, we first examined the association of KLF9 with PAFAH1B3 in pancreatic cancer tissues and cells." (PMID 38649699, 2024). "SW1990 and MIA Paca-2 cells ranked in the middle of all the pancreatic cancer cell lines in terms of PAFAH1B3 expression, and we selected these two cell lines for subsequent cell experiments." (PMID 38649699, 2024). "In conclusion, these results suggest that PAFAH1B3 can promote the proliferation, migration and metastasis of pancreatic cancer cells in vivo." (PMID 38649699, 2024). "In conclusion, our study indicated that KLF9 can inhibit the proliferation, invasion, migration and metastasis of pancreatic cancer cells by inhibiting PAFAH1B3." (PMID 38649699, 2024). "We also found that KLF9 inhibits the proliferation and metastasis of pancreatic cancer cells by downregulating PAFAH1B3 expression." (PMID 38649699, 2024). "The invasion and migration abilities of pancreatic cancer cells overexpressing PAFAH1B3 were assessed by scratch, transwell and invasion assays." (PMID 38649699, 2024). "The results showed that the overexpression of PAFAH1B3 significantly promoted the wound healing, invasion and migration ability of pancreatic cancer cells, which were significantly enhanced after the overexpression of PAFAH1B3 in vitro." (PMID 38649699, 2024). "In this study, we examined the effect of PAFAH1B3 expression on the invasion and migration of pancreatic cancer cells in vitro and in vivo." (PMID 38649699, 2024). "In conclusion, these results suggest that KLF9 inhibits the proliferation and metastasis of pancreatic cancer cells by downregulating PAFAH1B3 expression." (PMID 38649699, 2024). "The results showed that the expression of PAFAH1B3 in pancreatic cancer cell lines was significantly greater than that in normal pancreatic cells." (PMID 38649699, 2024). "Our results showed that overexpression of PAFAH1B3 significantly enhanced the tumorigenic ability of pancreatic cancer cells, and the percentage of Ki-67-positive tumours significantly increased." (PMID 38649699, 2024). "The invasion and migration abilities of pancreatic cancer cells with downregulated PAFAH1B3 expression were examined by scratch, transwell and invasion assays." (PMID 38649699, 2024). "In this study, we found that platelet-activating factor acetylhydrolase IB3 (PAFAH1B3) is highly expressed in pancreatic cancer tissues and cells." (PMID 38649699, 2024). "We found that KLF9 expression is negatively correlated with PAFAH1B3 expression in pancreatic cancer tissues and cells." (PMID 38649699, 2024). "In vitro and in vivo studies showed that overexpression of PAFAH1B3 promoted the proliferation and invasion of pancreatic cancer cells, while downregulation of PAFAH1B3 inhibited these processes." (PMID 38649699, 2024). "Overall, these results confirmed that PAFAH1B3 promotes the proliferation, invasion and migration of pancreatic cancer cells." (PMID 38649699, 2024). "The results showed that the PAFAH1B3 gene was significantly overexpressed in pancreatic cancer tissues compared with that in pancreatic tissues." (PMID 38649699, 2024). "In conclusion, these results suggest that PAFAH1B3 expression is inhibited by KLF9 in pancreatic cancer tissues and cells." (PMID 38649699, 2024). "Western blotting revealed that KLF9 negatively regulates the expression of PAFAH1B3 in pancreatic cancer tissues and cells." (PMID 38649699, 2024). "Taken together, our results suggested that PAFAH1B3 can upregulate PCNA expression in pancreatic cancer cells to promote their proliferation." (PMID 38649699, 2024). "Next, we further studied the effect of PAFAH1B3 on the proliferation of pancreatic cancer cells in vivo through subcutaneous tumour formation experiments in nude mice and measured the percentage of Ki-67-positive tumours." (PMID 38649699, 2024).
pancreatic cancer (continued). "Second, rescue experiments further demonstrated that KLF9 inhibits the proliferation, invasion and migration of pancreatic cancer cells by inhibiting the expression of PAFAH1B3." (PMID 38649699, 2024). "In vivo experimental results showed that the number of liver metastases formed by pancreatic cancer cells in the PAFAH1B3 overexpression group was significantly greater than that in the control group." (PMID 38649699, 2024). "Therefore, studying how to inhibit PAFAH1B3 expression in pancreatic cancer cells is of great clinical value." (PMID 38649699, 2024). "Interestingly, in this study, we measured the expression of PAFAH1B3 in pancreatic cancer tissues and cells, and the results showed that the expression of PAFAH1B3 in cancer tissues and cells was significantly increased." (PMID 38649699, 2024). "Rescue experiments showed that overexpression of PAFAH1B3 could partially attenuate the suppression of pancreatic cancer cell proliferation, invasion and migration induced by KLF9 overexpression." (PMID 38649699, 2024). "Furthermore, the mRNA expression of the PAFAH1B3 gene in 179 pancreatic cancer tissues and 171 pancreatic tissues in the TCGA and GTEx databases was analysed." (PMID 38649699, 2024). "Therefore, in vitro and in vivo experiments showed that the expression of PAFAH1B3 can promote the proliferation of pancreatic cancer cells." (PMID 38649699, 2024). "Exploring how to inhibit the expression of PAFAH1B3 in pancreatic cancer is worthwhile." (PMID 38649699, 2024). "Finally, we examined the regulatory effect of KLF9 on PAFAH1B3 at the pancreatic cancer cell level." (PMID 38649699, 2024). "Finally, the effect of PAFAH1B3 on the metastasis of pancreatic cancer cells in vivo was examined." (PMID 38649699, 2024). "However, whether PAFAH1B3 is involved in the mechanism by which KLF9 inhibits pancreatic cancer progression remains unclear." (PMID 38649699, 2024). "In addition, the expression of PAFAH1B3 mRNA and protein in pancreatic cancer cell lines (SW1990, MIA Paca-2, PANC-1, BxPC-3, CFPAC-1, and AsPC-1) and the human normal pancreatic ductal epithelial cell line HPDE6-C7 was measured by qRT‒PCR and Western blotting." (PMID 38649699, 2024). "To determine the effect of PAFAH1B3 expression on EMT in pancreatic cancer cells, we used Western blotting to detect changes in EMT-related proteins after the upregulation or downregulation of PAFAH1B3 in SW1990 and MIA Paca-2 cells." (PMID 38649699, 2024). "A rescue experiment was performed to confirm that PAFAH1B3 mediated KLF9 to inhibit the proliferation, invasion and metastasis of pancreatic cancer cells." (PMID 38649699, 2024). "Therefore, we hypothesized that KLF9 inhibits PAFAH1B3 expression in pancreatic cancer." (PMID 38649699, 2024). "Therefore, PAFAH1B3 may play a key role in the development of pancreatic cancer." (PMID 38649699, 2024). "To verify the effect of PAFAH1B3 on the biological behaviour of pancreatic cancer cells, we constructed the SW1990 and MIA Paca-2 cell lines with stable PAFAH1B3 overexpression via lentiviral transduction and verified the transduction efficiency by Western blotting." (PMID 38649699, 2024). "There was a negative correlation between KLF9 and PAFAH1B3 expression in pancreatic cancer tissues and cells." (PMID 38649699, 2024).
cancer (19 papers, 2018 to 2025). A tumor composed of atypical neoplastic, often pleomorphic cells that invade other tissues. "Platelet activating factor acetylhydrolase 1b catalytic subunit 3 (PAFAH1B3) has been implicated as a dysregulated metabolic gene associated with cancer processes including cell proliferation, apoptosis, and metastasis across various cancer types." (PMID 39553628, 2024). "PAFAH1B3, a platelet-activating factor acetylhydrolase that causes platelet-activating factor inactivation by deacetylation, is involved in the regulation of cancer development." (PMID 37957420, 2023). "Since PAFAH1B3 expression was associated with the pathology of many cancer types, the ability of PAFAH1B3 to prognose pan-cancer was explored." (PMID 35187070, 2021). "To evaluate the utility of PAFAH1B3 expression in predicting cancer patient prognosis, we analyzed the association between PAFAH1B3 expression and overall survival in the TCGA cohort." (PMID 33732641, 2021). "PAFAH1B3 genetic alterations were associated with overall survival, disease-specific survival, and progression-free interval in cancer patients." (PMID 35187070, 2021). "Furthermore, PAFAH1B3 has been implicated as a dysregulated metabolic gene associated with various cancer processes, including cell proliferation, apoptosis, and metastasis." (PMID 41009369, 2025). "PAFAH1B3 was also significantly associated with diverse drug sensitivity in many cancer cell lines and maybe a promising therapeutic target for cancer." (PMID 35187070, 2021). "Previous studies have indicated the association between PAFAH1B3 and cancer progression." (PMID 33732641, 2021). "TISIDB analysis showed that PAFAH1B3 expression was positively associated with genes for 28 tumor-infiltrating lymphocytes, 45 immune-stimulators, 24 immune-inhibitors, 41 chemokines, 18 receptors, and 21 MHCs in pan-cancer." (PMID 35187070, 2021). "The TISIDB tool showed that PAFAH1B3 expression was positively associated with genes for 28 tumor-infiltrating lymphocytes, 45 immune-stimulators, 24 immune-inhibitors, 41 chemokines, 18 receptors, and 21 MHCs in pan-cancer." (PMID 35187070, 2021). "Studies have shown that PAFAH1B3 is one of the most common lipid-metabolizing enzymes involved in cancer and promotes cancer progression." (PMID 38649699, 2024). "As a potential oncogene, PAFAH1B3 is one of the most common lipid-metabolizing enzymes and is highly expressed in cancer as a potential oncogene." (PMID 38649699, 2024). "PAFAH1B3 has been demonstrated to be involved in regulating the development of a variety of cancers." (PMID 38063949, 2023). "Our data showed that PAFAH1B3 was mainly localized in the cytoplasm of cancer cells and that the PAFAH1B3 protein level was prominently higher in 65 LUAD tissues than in paired adjacent noncanerous tissues (P < 0.01)." (PMID 35534807, 2022). "Recently, increasing evidence has indicated that platelet-activating factor acetylhydrolase 1b catalytic subunit 3 (PAFAH1B3) plays an important role in several cancers." (PMID 35534807, 2022). "PAFAH1B3 expression correlates significantly with pathology and poor prognosis and is highly accurate at predicting cancer progression." (PMID 35187070, 2021). "In summary, this study showed that PAFAH1B3 was elevated in multiple types of human cancer, and high expression correlated with poor prognosis." (PMID 35187070, 2021). "Our results show that PAFAH1B3 was highly expressed in a wide variety of malignant tumors compared with normal samples, including BLCA (P=3.20E-09), BRCA (P=3.20E-09)." (PMID 34490100, 2021). "In recent years, PAFAH1B3 was reported to play regulatory roles in various kinds of diseases, including human cancers." (PMID 33732641, 2021). "In recent years, PAFAH1B3, as a pan-cancer target, is found to be significantly upregulated in a variety of malignant tumors." (PMID 34490100, 2021).